HSPA2 (heat shock protein family A (Hsp70) member 2)
Description:
Molecular chaperone implicated in a wide variety of cellular processes, including protection of the proteome from stress, folding and transport of newly synthesized polypeptides, activation of proteolysis of misfolded proteins and the formation and dissociation of protein complexes. Plays a pivotal role in the protein quality control system, ensuring the correct folding of proteins, the re-folding of misfolded proteins and controlling the targeting of proteins for subsequent degradation. This is achieved through cycles of ATP binding, ATP hydrolysis and ADP release, mediated by co-chaperones. The affinity for polypeptides is regulated by its nucleotide bound state. In the ATP-bound form, it has a low affinity for substrate proteins. However, upon hydrolysis of the ATP to ADP, it undergoes a conformational change that increases its affinity for substrate proteins. It goes through repeated cycles of ATP hydrolysis and nucleotide exchange, which permits cycles of substrate binding and release. Plays a role in spermatogenesis. In association with SHCBP1L may participate in the maintenance of spindle integrity during meiosis in male germ cells (By similarity).
Synonyms: HSP70-2; HSP70-3
Tractability: Small molecule: a structure with a bound ligand is known; a high-quality ligand is known; it has a high-quality binding pocket. Antibody: its Gene Ontology location is reachable by antibodies, with medium confidence. PROTAC: ubiquitination databases record sites on it; its protein half-life has been measured; a small molecule that binds it is known.
Target class: Other cytosolic protein
Gene: Protein-coding gene on chromosome 14 (64,535,905 to 64,546,173, forward strand). Ensembl gene ENSG00000126803.
Subcellular location: Cytoplasm, cytoskeleton, spindle
Subcellular location (Human Protein Atlas): Annulus; Flagellar centriole; Vesicles; Calyx; Perinuclear theca
Pathways (Reactome):
Cellular responses to stimuli: Attenuation phase; HSP90 chaperone cycle for steroid hormone receptors (SHR) in the presence of ligand; Regulation of HSF1-mediated heat shock response
Immune System: PKR-mediated signaling
Reproduction: Meiotic synapsis
Gene Ontology:
Molecular function: enzyme binding; protein binding; ATP hydrolysis activity; heat shock protein binding; protein folding chaperone; ATP binding; glycolipid binding; protein-folding chaperone binding; tau protein binding
Biological process: negative regulation of inclusion body assembly; protein refolding; male meiotic nuclear division; response to cold; response to heat; response to unfolded protein; spermatid development; spermatogenesis
Cellular component: blood microparticle; cytosol; extracellular exosome; membrane; nucleus; CatSper complex; meiotic spindle; plasma membrane; cell surface; male germ cell nucleus; spindle; synaptonemal complex
Genetic constraint (gnomAD): Loss-of-function variants: 11 observed, 35.18 expected, observed/expected ratio (o/e) 0.31, 90% interval 0.2 to 0.52. The upper end of that interval is the gene's LOEUF score, 0.52, which puts it in group 2 of 6, group 1 being the genes least tolerant of losing a copy. Missense variants: 559 observed, 936.11 expected, observed/expected ratio (o/e) 0.6, 90% interval 0.56 to 0.64. Synonymous variants: 362 observed, 406.52 expected, observed/expected ratio (o/e) 0.89, 90% interval 0.82 to 0.97.
Homologues: Orthologues: chimpanzee HSPA2 (100% identical), dog HSPA2 (99% identical), mouse Hspa2 (98% identical), rat Hspa2 (98% identical), rabbit HSPA2 (98% identical), guinea pig HSPA2 (95% identical), tropical clawed frog hspa2 (87% identical), zebrafish hspa1b (85% identical), zebrafish hsp70.3 (83% identical), zebrafish hsp70.1 (83% identical), zebrafish hsp70.2 (83% identical), zebrafish hsp70l (83% identical), and 3 more. Paralogues in human: HSPA8 (87% identical), HSPA1A (84% identical), HSPA1B (84% identical), HSPA1L (82% identical), HSPA6 (78% identical), HSPA5 (63% identical), HSPA9 (50% identical), HSPA4 (34% identical), HSPA4L (32% identical), HSPH1 (32% identical), HYOU1 (30% identical), HSPA14 (29% identical), and 1 more.
Diseases named in the same sentence as HSPA2 in open-access papers:
HSPA2 is named in the same sentence as 80 diseases in open-access papers, as found by Europe PMC text mining. Sharing a sentence is not in itself a finding about the gene and the disease. The quoted sentences say what the papers report.
breast carcinoma (25 papers, 2010 to 2025). "For example, copy number amplification of HSPA2 was associated with its increased expression in breast cancer, glioblastoma multiforme, head and neck squamous carcinoma, lung squamous cell carcinoma, uterine corpus endometrial carcinoma and ovarian serous cystadenocarcinoma." (PMID 34712697, 2021). "Additionally, higher expression of HSPA2 was observed in ER- and PR-positive breast cancers which are linked to better clinical outcome." (PMID 31101846, 2019). "We suggest that HSPA1L and HSPA2 could represent potential biomarkers to follow up the effectiveness of 17AAG in breast cancer, although the mechanism underlying this effect is still unclear." (PMID 20920318, 2010). "RNF144A promotes ubiquitination degradation of YY1, inhibits tumor cell proliferation and migration, and promotes ubiquitination degradation of HSPA2, and these mechanisms lead to the inhibition of breast cancer by RNF144A." (PMID 40756570, 2025). "It was found that RNF144A interacts with the heat-shock protein family A member 2 (HSPA2), an oncoprotein, and promotes its ubiquitination degradation, thus negatively regulating breast cancer." (PMID 40756570, 2025). "According to Scieglinska D.’s research, HSPA2 was expressed in the majority of tumor histotypes including skin cancer, breast cancer, lung cancer, colon cancer, testis cancer, and so on." (PMID 37570716, 2023). "A recent study investigated novel therapeutic strategies in breast cancer via suppression of HSPA2‐mediated oncogenic signaling by specific small‐molecule inhibitors." (PMID 37306188, 2023). "Clinically, low RNF144A and high HSPA2 expression in breast cancer patients was correlated with aggressive clinico–pathological characteristics and decreased overall and disease-free survival." (PMID 34943954, 2021). "Apparently, HSP1A and HSPA8 are expressed in all breast cancer subtypes; HSPA2 is higher in luminal, while HSPA5 and HSPA6 are higher in basal subtypes." (PMID 34943954, 2021). "A similar response of HSF1 to MA that was accompanied by overproduction of HSPA1 and HSPA6 expression and HSPA2 downregulation was also observed in the wild type (wt) MCF7 breast cancer cell line." (PMID 34200371, 2021). "They found that RING finger protein 144A (RNF144A), a member of the RING-in-between-RING family of E3 ubiquitin ligases, functions as a tumor suppressor in breast cancer and target HSPA2 for degradation." (PMID 34943954, 2021). "In an animal study, the Proteintech antibody was used for HSPA2 detection in mouse testis, while in humans it was recently used to search for prognostic significance of HSPA2 in breast cancer." (PMID 32560263, 2020). "Observations that chemical pan-HSPA inhibitors effectively blocked the proliferation of NSCLC and breast cancer cells further confirm that HSPA2 and other HSPAs are redundant in their functions." (PMID 32987811, 2020). "Meanwhile, overexpression of HSPA2 was related to tumor angiogenesis and poor prognosis of pancreatic cancer, while the survival prognosis of breast cancer patients with high expression of NOX4 was poor, too." (PMID 33240321, 2020). "On the other hand, MM cell exposure to GSK260614 upregulated genes such as HSPA2 and HSPA1B, which are members of the heat-shock protein family and studies have shown that breast cancer patients overexpressing HSPA2 exhibited longer survival." (PMID 33028016, 2020). "Herein, using The Cancer Genome Atlas and KM plotter database, we showed strong association between expression of at least six HSP-encoding genes (namely: HSPA2, DNAJC20, HSP90AA1, CCT1, CCT2 and CCT6A) and survival of breast cancer patients." (PMID 31101846, 2019). "Collectively, these results suggest that high expression of HSPA2 and DNAJC20 is associated with low-risk breast cancer, whereas high expression of HSP90AA1, CCT1, CCT2 and CCT6A correlates with high-risk breast cancer." (PMID 31101846, 2019).
breast carcinoma (continued). "We also reported that breast cancer patients with low HSPA2 expression level had shorter overall survival time." (PMID 26576432, 2015). "During this process, HSPA2 was found with different characters in our breast cancer data compared with previous reported study in other cancer types." (PMID 26576432, 2015). "We would like to ask biomedical researchers to study the HSPA2 in breast cancer to understand the real biological function of this biomarker." (PMID 26576432, 2015). "HSPA2 has been identified as a potential cancer-promoting protein expressed at abnormal levels in a subset of human cancers, such as breast cancer, cervical cancer, bladder urothelial cancer, nasopharyngeal carcinoma and malignant tumors." (PMID 23777267, 2013). "Overexpression of HSPA2 is correlated with poor therapeutic outcomes in human breast cancer, cervical cancer and bladder urothelial cancer; furthermore, it is now a valuable prognostic marker for breast cancer patients." (PMID 23777267, 2013). "Moreover, RNF144A-mediated suppression of breast cancer cell proliferation, migration, and invasion was rescued by ectopic HSPA2 expression." (PMID 34943954, 2021). "Therefore, HSPA2 seems to be involved in the pathogenesis of breast cancer by sustaining viability, promoting motility, migration and invasion." (PMID 34943954, 2021). "A recent study indicated that HSPA2 might play an important role in breast cancer development and progression by promoting cell growth, migration and invasion in xenografted mice." (PMID 33785008, 2021). "Notably, the ligase activity-defective mutants of RNF144A impaired its ability to induce ubiquitination and degradation of HSPA2, and to suppress breast cancer malignant phenotype as compared with its wild-type counterpart." (PMID 34943954, 2021). "Ambiguities observed in breast cancer, may result either from the fact that HSPA2 expression is regulated at posttranscriptional level or, alternatively, from some technical limitations in HSPA2 detection." (PMID 32560263, 2020). "Contrary to our findings, a recent study indicated that HSPA2 might also play an essential role in breast cancer development and progression by promoting cell growth and cellular motility both in culture as well as in vivo in xenotransplanted mice." (PMID 31101846, 2019). "But the results of this study show that HSPA2 plays a totally different role in breast cancer." (PMID 26576432, 2015). "We found that HSPA2 plays a different role in breast cancer through our bioinformatics approaches." (PMID 26576432, 2015). "“....HSPA1L and HSPA2 could represent potential biomarkers to follow up the effectiveness of 17AAG in breast cancer”." (PMID 23216862, 2012). "Through ubiquitin ligase activity-dependent modulation of HSPA2′s stability and carcinogenic properties, RNF144A suppresses tumors in breast cancer." (PMID 38313020, 2024). "We compared the effect of proteasome inhibition on HSPA2 expression in NCI-H1299, NCI-H23 and MCF7 cancer cell lines derived from non-small cell lung cancer (NSCLC) and breast cancer, respectively." (PMID 36959387, 2023). "HSPA2 (HSP70-2) is known to be involved in spermatogenesis and also plays a role in breast cancer (considered in detail in Section 4.1)." (PMID 34943954, 2021). "Apparently, although HSP70 is a close homologue of HSPA2, it cannot completely substitute its function, and vice versa, and therefore knockdown of either HSPA2 or HSP70 has profound effect on survival and tumorigenicity of breast cancer cells." (PMID 34943954, 2021). "HSPA2 and HSPA1A were mainly expressed in lung cancer and breast cancer cell lines." (PMID 34712697, 2021). "For breast cancer, we select five essential genes, such as CTSA, HSPA2, RNASE1, CLIC6, IFITM1." (PMID 33133130, 2020).
breast carcinoma (continued). "Interestingly, patients overexpressing two identified HSPs – HSPA2 and DNAJC20 exhibited longer survival, whereas overexpression of other four HSPs – HSP90AA1, CCT1, CCT2, CCT6A resulted in unfavorable prognosis for breast cancer patients." (PMID 31101846, 2019). "In addition, even the triple knockdown of HSPA1A/B, HSPA5, and HSPA2 expression did not decrease the viability of breast cancer MDA-MB-468 cells." (PMID 32987811, 2020).
infertile (12 papers, 2012 to 2025). "We suggest that the alternations in the level of intracellular anion superoxide, percentages of HSPA2 and protamine positive spermatozoa might be causes of infertility in terato-asthenozoospermic men." (PMID 28744523, 2017). "The importance of HSPA2 during spermatogenesis and fertilization has been previously established given the infertility phenotype of knockout for this gene in mice." (PMID 35819578, 2023). "The most relevant studies in human samples have reported reduced levels of HSPA2 expression in samples from patients suffering varicocele, elevated ROS (reactive oxygen species) levels, infertility, or disability to bind to the ZP." (PMID 35819578, 2023). "In this regard, HSPA2 expression has proven to be significantly higher in fertile compared to infertile individuals." (PMID 35163651, 2022). "Deletion of Eif4g3 affects Hspa2 translation and inhibits sperm formation during the meiosis stage, leading to infertility." (PMID 34312369, 2021). "Among the proteins that interact with these proteins, the expression levels of Hspa2 and Eif4g3 proteins were significantly reduced in the infertile group because of Ubb-knockout as compared to that in WT mice." (PMID 34312369, 2021). "In summary, by experimentally disrupting the male germ cell orthoBackbone across evolutionarily distant species, we were able to uncover two new candidate genes for human infertility (HSPA2 and KPNA2) in addition to RNF113B, affecting a combined total of five individuals." (PMID 39388236, 2024). "We suggest that the increase in intracellular O2–, decrease in spermatozoa HSPA2+, and high percentages of spermatozoa with immature chromatin might be considered as etiologies of infertility in TA patients." (PMID 28744523, 2017). "Therefore, the downregulation of HSPA2, BAG6, and SPA17 in the present study indicates that sperm and oocyte recognition may be associated with the abnormal sperm linked with infertility." (PMID 34213690, 2021). "It follows that sub-classes of infertile males, such as cryptozoospermic patients, have low to non-detectable seminal plasma HSPA2; likely reflective of an almost total meiosis arrest." (PMID 36909306, 2023). "A lack of HSPA2 is found in infertile patients with defective ZP-binding ability." (PMID 37020592, 2023).
male infertility (10 papers, 2011 to 2025). The inability of the male to effect fertilization of an ovum after a specified period of unprotected intercourse. "Deficiency of Bat3, or HSPBP1, in knockout (KO) mice leads to male infertility caused by impaired spermatogenesis with morphological features similar to those observed in HSPA2 null mice." (PMID 25344376, 2015). "Filtering these exomes for LoF variants in the 27 selected orthoBackbone genes revealed two new human male infertility candidate genes: HSPA2 and KPNA2." (PMID 39388236, 2024). "The translational application of our cross-species platform in human reproductive healthcare has so far uncovered three new genes associated with human male infertility (RNF113B, HSPA2, and KPNA2)." (PMID 39388236, 2024). "(j) LoF variants in the orthoBackbone genes HSPA2 and KPNA2 are potentially associated with human male infertility." (PMID 39388236, 2024). "Knockouts of EL52, AKAP4, ODF2 and HSPA2 showed phenotypic alterations in sperm physiology and morphology, which resulted in male infertility." (PMID 34697378, 2021). "In animal models, targeted gene disruption of HSPA2 resulted in meiosis failure, increased apoptosis and male infertility." (PMID 32120839, 2020). "Aberrant expression of HSPA2 in testes induced primary spermatocytes to arrest in meiosis I and undergo apoptosis, which was leading to male infertility." (PMID 23777267, 2013). "The Hspa2 gene is located on chromosome 14 (14q24.1), and the aberrant expression of HSPA2 in testes was shown to induce primary spermatocytes to arrest in meiosis I and undergo apoptosis, thus leading to male infertility." (PMID 40063400, 2025). "During meiosis, spermatogenic cells synthesize HSPA2, knockout of HSPA2 in HSPA2 (−/−) male mice testes induce primary spermatocytes to arrest in meiosis I and undergo a dramatic increase in spermatocyte apoptosis, which was leading to male infertility." (PMID 23777267, 2013). "Interestingly, the interaction of HSPA2 with BAG6 (BCL2-associated athanogene 6; formerly BAT3, HLA-B-associated transcript 3) has been demonstrated to regulate its stability thereby making BAG6 a molecular target for idiopathic male infertility." (PMID 39005499, 2024). "Recently, an association between impaired fertilizing ability of sperm from patients diagnosed with idiopathic male infertility and a total lack of HSPA2 in their sperm has been reported." (PMID 25344376, 2015).
hepatocellular carcinoma (7 papers, 2015 to 2022). A malignant tumor that arises from hepatocytes. "Similarly, increased HSPA2 in pancreatic ductal adenocarcinoma and hepatocellular carcinoma was associated with more aggressive clinical features and shorter overall survival." (PMID 31101846, 2019). "The polymorphism of HSPA2 at position 1267 has been suggested to be associated with carcinogenesis in several malignant cancer tissues, such as lung cancer, cervical cancer, esophageal squamous cell carcinoma, and hepatocellular carcinoma." (PMID 25890028, 2015). "The anti-HSPA2 antibody marketed by Santa Cruz Biotechnology was used in studies on prognostic value of HSPA2 in hepatocellular carcinoma and esophageal SSC." (PMID 32560263, 2020). "In fact, hypoxia increased the HSPA2 expression in human hepatoma (HepG2), breast (MCF-7), and cervical (HeLa) cancer cells." (PMID 25344376, 2015). "The overexpression of HSPA2 has been identified in several human malignancies, including non-small cell lung cancer, cervical carcinoma, esophageal squamous cell carcinoma, and hepatocellular carcinoma." (PMID 25890028, 2015). "So far, a high level of HSPA2 in tumor was reported as a negative prognostic factor in esophageal cancer, hepatocellular cancer, pancreatic cancer, and NSCLC." (PMID 32987811, 2020).
varicocele (7 papers, 2017 to 2024). A condition characterized by the dilated tortuous veins of the spermatic cord with a marked left-sided predominance. "Otherwise, previous studies have demonstrated a positive relationship among HSPA2 expression and fertility potential of a semen sample in patients with ZP binding deficiency and varicocele." (PMID 35819578, 2023). "One study used a varicocele model to evaluate the effect of resveratrol, a naturally occurring polyphenol, and discovered decreased protein expression of protamine I/II and HSPA2." (PMID 38392299, 2024). "In humans, the HSPA2 gene expression is downregulated in men with azoospermia, varicocele and oligozoospermia, and idiopathic oligoteratozoospermia." (PMID 37020592, 2023). "Several studies have reported that the expression of HSPA2 increased at the transcriptional level in spermatogenic cells and induced apoptosis in testicular spermatogenic cells in the varicocele group compared to the control group." (PMID 35592276, 2022). "HSPA2 mRNA and protein expression levels were lower in oligozoospermic men with varicocele, but HSPA2 protein activity increased after varicocele resection." (PMID 35401656, 2022). "Also, there was a significant increase in Bax, HSPA2, and HIF1‐α expressions in the varicocele group compared to the control group." (PMID 35592276, 2022).